FBXW7 (F-box and WD repeat domain containing 7)
Diseases named in the same sentence as FBXW7 in open-access papers (continued):
Sharing a sentence is not in itself a finding about the gene and the disease.
tumor (continued). "More interestingly, serial tumor profiling also allowed us to identify a panel of mutated genes enriched and present at baseline and persisting through the end of CRT including FBXW7, LRP1B, and RYR2." (PMID 36201462, 2022). "RB1 and FBXW7 are the classical tumor suppressor genes, and their deletion or inactivation has been reported to be implicated in tumorigenesis." (PMID 36035135, 2022). "In the past decade, as an E3 ligase, FBXW7 has been found to play numerous roles in cancers including angiogenesis, tumor initiation and progression, proliferation, and differentiation." (PMID 35651754, 2022). "FBXW7 acts as a substrate recognition unit of an E3 ubiquitin protein ligase and has been identified as a tumour suppressor gene in other cancers." (PMID 35231161, 2022). "F-box and WD repeat domain-containing 7 (Fbw7) is well known as a tumor suppressor and ubiquitin ligase which targets a variety of oncogenic proteins for proteolysis." (PMID 35359405, 2022). "The protein F-box and WD repeat domain containing 7 (FBXW7) is a subunit of an E3 ubiquitin ligase and is considered to have a tumor suppressor function." (PMID 35651754, 2022). "To understand the effect of miR‐30e on modulation of ubiquitin proteosome pathway (UPS), we examined expression of FBXW7, a E3 ubiquitin ligase tumor suppressor and one of the targets of FBXO45." (PMID 35612714, 2022). "We revealed for the first time that SEMA3B-AS1 can bind HMGB1 to promote the transcription and expression of FBXW7, thus exerting its tumor suppressive effect." (PMID 35273678, 2022). "FBXW7, as a critical tumor suppressor of human cancers, controls proteasome-mediated degradation of oncoproteins." (PMID 35844805, 2022). "Further investigations showed that KDM5B accumulated CCNE1 in tumor cells by decreasing the expression of FBXW7, which resulted in the acceleration of G1/S cell cycle phase transition and finally promoted malignant proliferation." (PMID 35428764, 2022). "Serving as a suppressor protein, FBXW7 attenuates tumor stemness by orchestrating different pathways." (PMID 35515121, 2022). "Mechanistically, as a direct upstream transcription factor, FBXO9 is regulated by zinc finger protein 143 (ZNF143) and accelerates tumor growth and metastasis by targeting the F-box and WD repeat domain containing 7 (FBXW7) for ubiquitination and degradation." (PMID 35847937, 2022). "FBXW7 roles as a tumor suppressor on account of promoting the degradation of various oncogenes including Cyclin E, c-Jun, Notch, mTOR, c-Myc, etc.." (PMID 36591289, 2022). "FBXW7, one of the F-box protein family members, function as a tumor-suppressing gene in various human cancers." (PMID 35094292, 2022). "FBXW7, which acts as a critical tumor suppressor of human cancers, controls proteasome-mediated degradation of oncoproteins." (PMID 35844805, 2022). "FBXW7 affects many regulatory functions involved in cell survival, cell proliferation, tumor invasion, DNA damage repair, genomic instability and telomere biology." (PMID 35346215, 2022). "Studies have demonstrated that FBXW7 is involved in the regulation of immune evasion occurring both in anti-virus and anti-tumor immunoreaction." (PMID 35814468, 2022). "FBXW7 is an important tumor suppressor and is responsible for the ubiquitylation and proteasomal degradation of c-Myc." (PMID 35064102, 2022). "FBXW7 also modulates the tumor immune microenvironment by mediating the degradation of C/EBPδ, thereby inhibiting Toll-like receptor 4 expression, reducing inflammation, and modulating the innate immune response of macrophages to pathogens." (PMID 35346215, 2022). "It has been well-known that the tumor suppressor FBXW7 belongs to the F-box protein (FBP) family and is a component of SCF (SKP1/CUL1/F-box) E3 ubiquitin ligase." (PMID 35338113, 2022). "Previous studies have indicated that the downregulation of FBXW7 facilitates tumor cell migration and invasion through inducing EMT in RCC." (PMID 35295711, 2022).
tumor (continued). "The upregulation of FBXW7-185aa in glioblastoma cancer cells inhibits both the proliferation of tumor cells and the progression of the cell cycle." (PMID 35595755, 2022). "FBXW1 as an oncogene and FBXW7 as a tumor suppressive gene also show opposite relationships on immune infiltration cells." (PMID 36591289, 2022). "It is well known that FBXW7 serves as a tumor suppressor that promotes ubiquitination of a wide range of oncoproteins for proteasomal degradation, including mTOR." (PMID 35847937, 2022). "F-box and WD repeat domain containing 7 (FBXW7) is well studied and acts as one tumor suppressor gene in human carcinogenesis and tumor progression." (PMID 35928868, 2022). "FBXW7 is a tumor suppressor and regulates the TGF-β/BMP-pathway by targeting for degradation co-repressor TGF-β-induced factor 1 (TGIF1), which recruits specific repressor complexes to SMAD2." (PMID 35805024, 2022). "It has been reported that FBXW7 is usually low expressed in many human cancers and is well recognized as a tumor suppressor gene." (PMID 35428764, 2022). "Although the physiological role of the ERK3 protein remains controversial, our results consistently support the idea that FBXW7 acts as a tumor suppressor." (PMID 35022544, 2022). "POLE ultra-mutated tumours exhibit few copy number aberrations and have mutations in PTEN, PIK3RI, PIK3CA, FBXW7 and KRAS genes." (PMID 35530346, 2022). "Overexpression of circ-11780 inhibits the proliferation, migration, and invasion of NSCLC cells in vitro and tumor growth in vivo via the miR-544a overexpression and reduced the protein concentration of F-Box and WD repeat domain containing 7 (FBXW7)." (PMID 36338714, 2022). "FBXW7 is considered to be a strong tumor suppressor that governs human cell cycle progression, cell growth, and tumor development by directing certain oncoproteins to ubiquitin-mediated proteolysis." (PMID 33494392, 2021). "Fbxw7 has immunoregulatory capacities, it controls effector T cell polyfunctionality and survival in tumor environment by inhibiting Notch activation." (PMID 35069531, 2021). "As a member of the F-box protein family, FBXW7 is an important tumor-suppressor gene and one of the most-commonly deregulated ubiquitin-proteasome system proteins in human cancers." (PMID 34659544, 2021). "Taken together, these data suggest that the METTL3-FBXW7 axis contributes to inhibition of tumor growth in vivo and that targeting m6A-modified FBXW7 is a promising strategy for overcoming tumorigenesis in LUAD." (PMID 33676554, 2021). "FBXW7 regulates tumor size and tumor cell mitosis and hence plays a key role in the progression of GISTs." (PMID 33822486, 2021). "Dysfunctional FBXW7 is responsible for defects in antigen peptide formation and presentation of tumor development and malignancies." (PMID 34912899, 2021). "Taken together, these results indicated that RANBP10 promoted colony formation and tumor growth of GBM cells by targeting the FBXW7/c-Myc signaling pathway." (PMID 34671019, 2021). "In summary, this study revealed that circSLC30A7 is an essential tumor suppressor that inhibits HCC tumorigenesis through the miR-767-5p/FBXW7/NOTCH1 axis." (PMID 34675978, 2021). "FBXW7 is a key substrate recognition subunit of the SCF complex that acts as a tumor suppressor gene by controlling the proteasome-mediated degradation of oncoproteins, such as c-MYC, MCL1, Notch1/4, cyclin E, and mTOR." (PMID 33676554, 2021). "FBXW7, a critical tumor suppressor in many types of cancer, regulates the proteasome-mediated degradation of oncoproteins including MYC." (PMID 33494392, 2021). "Consistent with its role as a tumor suppressor, the mutation of the FBXW7 gene was found in around 6% of all human cancers, which not only abrogates the tumor suppressive activity of FBW7, but also endows these mutants with the oncogenic function." (PMID 33658012, 2021).
tumor (continued). "By selectively targeting many oncoproteins for proteasome-mediated degradation, FBXW7 acts as a typical tumor suppressor." (PMID 34760892, 2021). "For example, FBXW7 is also regarded as a tumor suppressor and inactivation of FBXW7 can increase resistance to anti-tubulin drugs and promote tumorigenesis." (PMID 34512273, 2021). "During activation of Wnt/LRP6 signaling, the kinase GSK-β which phosphorylates β-catenin, and FbXW7 substrates, such as c-Myc, are sequestered, resulting in the stabilization of β-catenin, c-Myc, and other critical tumor-promoting regulators." (PMID 34572023, 2021). "Our findings reveal that METTL3 positively regulates FBXW7 expression and confirm the tumor-suppressive role of m6A-modified FBXW7, thus providing insight into its epigenetic regulatory mechanisms in LUAD initiation and development." (PMID 33676554, 2021). "FBXW7 is a critical tumor suppressor that regulates proteasome-mediated degradation of various oncoproteins, such as cyclin E, c-Myc, Mcl-1, mTOR, Jun, Notch and AURKA in human cancer." (PMID 33450701, 2021). "In our study, both in vivo and in vitro data showed that phosphorylation at the T205 site inhibited FBXW7 tumor suppressor function in MB." (PMID 33494392, 2021). "FBXO45 induces the ubiquitination–proteasomal degradation of several tumor-suppressor proteins, such as Par4 (prostate apoptosis response protein 4), F-box/WD repeat-containing protein 7 (FBXW7), and p73." (PMID 33921128, 2021). "FBXW7 is a critical tumour suppressor involved in the ubiquitin-proteasome system in human cancer, and loss of FBXW7 function leads to chromosomal instability." (PMID 34660277, 2021). "F-Box and WD repeat domain containing 7 (FBXW7) can inhibit tumor development by acting on the tumor microenvironment." (PMID 34925002, 2021). "F-box and WD repeat domain-containing 7 (FBXW7) is a classical tumor suppressor that promotes the ubiquitination and degradation of several oncoproteins, such as Cyclin E, c-MYC, and c-JUN." (PMID 34912714, 2021). "FBXW7 is a well‐known tumor suppressor that limits tumor cell proliferation, thereby supporting the absolute necessity for its inactivation in progressive tumors." (PMID 33822486, 2021). "In B-lymphoma murine models, xenografted tumors bearing CREBBP/EP300 mutation presented lower H3K27 acetylation, higher M2 macrophage recruitment, and more rapid tumor growth than those with CREBBP/EP300 wild-type control via FBXW7-NOTCH-CCL2/CSF1 axis." (PMID 33431788, 2021). "FBXW7 is responsible for degrading diverse oncoproteins and is considered a tumor suppressor in many types of cancers." (PMID 33494392, 2021). "Essentially, FBXW7 is itself a tumor suppressor, the regulatory network of which is disturbed in many human carcinomas." (PMID 33822486, 2021). "We show that MYC activates PLK1 transcription, while the inhibition of PLK1 suppresses MB tumor development and causes a decrease in c-MYC protein level by suppressing FBXW7 auto poly-ubiquitination." (PMID 33494392, 2021). "Many studies have shown that FBXW7 expression is reversely correlated with enhanced tumor proliferation and migration." (PMID 34766156, 2021). "The E3 ubiquitin ligase Fbxw7 has been well characterized as a critical tumor suppressor that can mediate the degradation of various oncoproteins by the ubiquitin-proteasome system." (PMID 35069531, 2021). "Significantly more tumors were derived from shMETTL3 HCC827 cells than from HCC827 Ctrl cells; however, FBXW7 overexpression attenuated the tumor-promoting effect of shMETTL3 HCC827 cells in vivo." (PMID 33676554, 2021). "FBXW7 is well-known for its tumor suppressor function against cancer development by targeting a variety of oncoproteins for proteasomal degradation." (PMID 34760892, 2021). "Our findings indicate that FBXW7 expression is positively associated with METTL3 at the protein level and exerted a crucial tumor suppressor function in carcinogenesis." (PMID 33676554, 2021).
tumor (continued). "The most frequently mutated genes are the tumor suppressors PTEN and FBXW7, which are both mutated in 14.9% of cases in PIK3CA mutated cancers and in 5% and 10.6% of cases, respectively, in PIK3CA wild-type cancers." (PMID 33435133, 2021). "As a tumor suppressor in the process of human carcinogenesis, Fbxw7 is often observed to be downregulated in a variety of human cancers and is associated with a poor prognosis." (PMID 34616431, 2021). "Mounting studies have demonstrated that FBXW7 plays critical roles in tumor initiation, cell proliferation, cell differentiation and angiogenesis." (PMID 35712679, 2021). "In contrast, Pin‐1 deficiency leads to FBXW7 overexpression that subsequently limits MCL‐1 expression, thereby sensitizing the tumor cells to drugs like Taxol." (PMID 33822486, 2021). "In summary, these data indicated that Dem suppressed tumor growth through regulating the FBXW7/c‐Myc axis in GC." (PMID 34766156, 2021). "F-box and WD repeat domain containing 7 (FBXW7) is identified as a tumor-suppressive factor and exerts an inhibitory role in HCC cell growth by regulating Yes-associated protein (YAP) degradation." (PMID 34790050, 2021). "Previous articles have demonstrated the role of ubiquitin ligase FBXW7 in regulating tumor metastasis and epithelial-mesenchymal transition." (PMID 33391437, 2021). "The human FBXW7 gene is reportedly deleted in approximately 30% of all cancer types, thereby underscoring its role in tumor progression and prognosis." (PMID 33822486, 2021). "F-box and WD repeat domain containing 7 (FBXW7), a member of the F-box protein family, which has been reported to function as a tumor suppressor in various human cancers." (PMID 32182776, 2020). "Here, we investigated the role of myeloid cell-specific FBXW7-knockout on tumor progression in mice and on M2-like TAMs." (PMID 33260160, 2020). "Among thousands of predicted target genes of miR-92a-3p, FBXW7, a tumor suppressor, was one of the top five precited target genes of miR-92a-3p in both softwares." (PMID 32140077, 2020). "The tumour suppressor FBXW7 binds to proto-oncogenes mediating degradation, while dysregulation leads to chromosomal instability and tumourigenesis due to accumulation of oncoproteins." (PMID 32198650, 2020). "Ablation of Fbxw7 in mouse bone marrow-derived stromal cells was thus found to promote metastatic tumor growth in a manner dependent on Notch1 accumulation and activation of Ccl2 transcription." (PMID 32429232, 2020). "F-box/WD repeat-containing protein 7 (FBXW7), a general tumor suppressor in human tumorigenesis, is another key E3 ubiquitin ligase." (PMID 32272746, 2020). "While our work identified a novel role of FBXW7 in suppressing tumor growth, there are still notable questions that remain to be addressed." (PMID 33260160, 2020). "Most of the cells in cluster 2 were from tumours of P0909 (NOTCH1 and FBXW7 mutations) and P1012 (NOTCH1 mutation), and most of the cells in cluster 4 were from tumour of P0701 (two types of FBXW7 mutations)." (PMID 32924269, 2020). "As a member of E3 complex, FBXW7 exerted its tumor suppressor function via targeting oncogenes (such as YAP1) for degradation." (PMID 32140077, 2020). "FBXW7 knockout in mouse embryonic fibroblasts induces the epithelial-to-mesenchymal transition to promote tumor metastasis." (PMID 33260160, 2020).
tumor (continued). "Because these substrates are generally considered as proto-oncogene proteins that are widely involved in the tumorigenesis of human cancers, FBXW7 has been recognized as a tumor suppressor for its ability to mediate the degradation of these proteins." (PMID 32175272, 2020). "We have previously reported novel mutations in the WD40 domain of FBXW7 preventing degradation of NOTCH1 in ATL cells and decreased in vivo tumor growth by blockade of NOTCH1-dependent growth of ATL cells." (PMID 32907612, 2020). "FBXW7 is regarded as a potent tumour suppressor in different human cancers, as most of its target substrates can function as potential growth promoters." (PMID 32588541, 2020). "For example, FBXW7 acts as a tumor suppressor by targeting mTOR, HIF-1α, c-Myc and SREBP1 for degradation." (PMID 33004065, 2020). "We found that the tumor weight was significantly increased in mice with FBXW7 knockout in myeloid cells." (PMID 33260160, 2020). "It is now well established that FBXW7 functions as a tumor suppressor that promotes apoptosis in human tumor cells." (PMID 32239181, 2020). "It is reported that FBXW7 acts as a tumor suppressor through the assembly of SCF E3 ubiquitin ligases as well." (PMID 32175272, 2020). "There’s a study testified that low FBXW7 expression levels in cancers lead to malignant potential, for example tumor size, lymph node metastasis and poor prognosis." (PMID 32239181, 2020). "Of note, FBXW7 functions as a tumor suppressor in various types of human cancers, due to its capability to suppress cell growth, invasion and migration." (PMID 32159214, 2020). "Although most research on the role of FBXW7 in cancer has focused on its tumor suppressor function in cancer cells themselves, FBXW7 also suppresses cancer metastasis by inhibiting cancer niche formation by noncancer cells." (PMID 32429232, 2020). "FBXW7 is considered a critical tumor suppressor of human cancers because it degrades important oncoproteins such as c-MYC, cyclin E, MCL1, mTOR, c-JUN, PLK1, NOTCH or AURKA." (PMID 32316282, 2020). "Bioinformatic analysis, RT-qPCR, RNA pull down assay and dual luciferase assay showed that FER1L4 upregulated F-box/WD repeat-containing protein 7 (FBXW7) tumor suppressor via sponging miR-92a-3p." (PMID 32140077, 2020). "FBXW7 deletion in tumor cells determines the fate of tumor cells through limiting oncoprotein ubiquitin-mediated proteolysis and promoting their aberrant accumulation." (PMID 33260160, 2020). "It has been accepted that FBXW7 exerts its tumour-suppressive function by targeting its substrates for ubiquitination and degradation, including Notch, c-Jun, cyclin E, c-Myc and Mcl-1." (PMID 32655893, 2020). "The appearance of the tumors in two groups was evaluated and indicated that FBXW7 depletion in myeloid cells promoted tumor development." (PMID 33260160, 2020). "F-box and WD-40 domain protein 7 (FBXW7), a classical tumor suppressor, was found directly targeted by miR-27a and its translation was suppressed by miR-27a in OC cells." (PMID 32159214, 2020). "FBXW7 is a typical tumor suppressor and can target a series of key human oncoproteins, such as cyclin E, c-JUN, c-MYC, NOTCH-1, and MCL-1." (PMID 33708617, 2020). "In the previous studies, FBXW7 often acted as a tumor suppressor in hepatocellular carcinoma, colorectal cancer, non‐small‐cell lung cancer, breast and ovarian cancer cells (Zhao, Wang, Mu, Xu, & Sang, 2017), and others." (PMID 32369227, 2020). "Recent work has shown that FBXW7 expression was downregulated in T-cell lymphoblastic lymphoma, which is in accordance with its tumor suppressor function." (PMID 32175272, 2020). "F-box/WD repeat-containing protein 7 (FBXW7) is a tumor suppressor and one of the major targets of miR-223-3p." (PMID 32235691, 2020).